EIF3A (eukaryotic translation initiation factor 3 subunit A)
Diseases named in the same sentence as EIF3A in open-access papers (continued):
Sharing a sentence is not in itself a finding about the gene and the disease.
pulmonary fibrosis (3 papers, 2022 to 2025). Chronic progressive interstitial lung disorder characterized by the replacement of the lung tissue by connective tissue, leading to progressive dyspnea, respiratory failure, or right heart failure. "With the increasing understanding of the physiological and pathological functions of eIF3a, it has gradually become important in cardiac and pulmonary fibrosis." (PMID 40346622, 2025). "Inhibit the expression of eIF3a induced by NF-κB pathway activation, thereby alleviating pulmonary fibrosis." (PMID 39301028, 2024). "Further, one study showed that low doses of CPS alleviated bleomycin-induced lung fibrosis via inhibiting ERK1/2/eIF3a signaling in the alveolar epithelial cells." (PMID 35212819, 2022).
acute myeloid leukemia (2 papers, 2024). Acute myeloid leukemia (AML) is a group of neoplasms arising from precursor cells committed to the myeloid cell-line differentiation. "Among them, increased eIF3a expression were observed in 21 types of tumors, which included acute lymphoblastic leukemia (ALL) and acute myeloid leukemia (AML) (P < 0.05)." (PMID 38589831, 2024). "IGF2BP2 recruits proteins such as eIF4E and eIF3A to MYC, GPT2, and SLC1A5 mRNA, regulating glutamine metabolism in acute myeloid leukemia and modulating the immune response of macrophages through epigenetic reprogramming." (PMID 39726589, 2024).
adenoma (2 papers, 2019 to 2024). A neoplasm arising from the epithelium. "Additionally, the expression of both eIF3a and eIF3i but not eIF3b and eIF3g is also increased in benign adenoma polyps." (PMID 39413959, 2024).
clear cell renal cell carcinoma (2 papers, 2021 to 2024). "Next, to further investigate the role of EIF3A in immunity, we explored the relationship between EIF3A expression and markers of different immune cell types in renal clear cell carcinoma." (PMID 34923969, 2021). "To investigate the potential pathogenesis of EIF3A in ccRCC, we analysed the coexpression genes of EIF3A in renal clear cell carcinoma by using the LinkedOmics database." (PMID 34923969, 2021). "In clear cell renal cell carcinoma, EIF3A expression is lower in the tumour tissue." (PMID 34923969, 2021). "We hypothesized that LTV1 and EIF3A could jointly promote the tumorigenesis of clear cell renal cell carcinoma and significantly affect the prognosis." (PMID 34923969, 2021). "The impact of EIF3A in clear cell renal cell carcinoma (ccRCC) has yet to be reported." (PMID 34923969, 2021).
kidney cancer (2 papers, 2019 to 2020). Primary or metastatic malignant neoplasm involving the kidney. "Synergistic effects may occur through the interaction of EIF3A (Eukaryotic Translation Initiation Factor 3 Subunit A) and METTL14, which regulates kidney cancer progression." (PMID 32765970, 2020). "In contrast, our study enabled prioritizing 138 genes based on a refined set of putative somatic SNVs, where 49 of those genes had previously been related to kidney cancer according to the literature, and two genes (SIPA1L2 and EIF3A) were validated in independent datasets from TCGA." (PMID 31156702, 2019).
liver cancer (2 papers, 2019 to 2023). An epithelial or non-epithelial malignant neoplasm that arises from the liver. "IHC analysis of a human liver cancer tissue microarray confirmed high EIF3A expression compared to normal tissue, which indicates that EIF3A overexpression may be induced during HCC progression." (PMID 31363116, 2019).
Merkel cell carcinoma (2 papers, 2020 to 2023). "Overall, our study could establish a novel tumorigenic mechanism in fatal skin cancer, Merkel cell carcinoma, that happens due to the upregulation YTHDF1 m6A reader, and by activation of translational initiation factors eIF3A and 3B." (PMID 31947544, 2020).
Obesity (2 papers, 2023 to 2025). Accumulation of substantial excess body fat. "It is promising for eIF3a to play roles in obesity, fatty liver, diabetes, infectious diseases, autoimmune diseases, tumor immunity, and inflammation." (PMID 37152897, 2023).
renal cell carcinoma (2 papers, 2020 to 2021). "GSEA results indicated that EIF3A high expression was enriched in the renal cell carcinoma pathway." (PMID 34923969, 2021).
adrenocortical carcinoma (1 paper, 2024). "High eIF3a expression were demonstrated to be correlated with worse outcome in 3 tumors including AML, bladder urothelial carcinoma (BLCA) and adrenocortical carcinoma (ACC)." (PMID 38589831, 2024).
Burkitt lymphoma (1 paper, 2023). A rare form of malignant mature B-cell non-Hodgkin lymphoma. "We engineered Ramos Burkitt’s lymphoma cell lines expressing the CT or HLH* EIF3A using the shRNA method as in HEK293T cells and observed a substantial decrease in MYC and MET protein levels in the lymphoma cells expressing the HLH* EIF3A." (PMID 37768948, 2023). "To test whether the molecular insights gained using HLH* EIF3A could have physiological implications in cancer, we generated HLH* EIF3A expressing Ramos Burkitt’s lymphoma cell lines, which are dependent on MYC overexpression for their proliferation." (PMID 37768948, 2023). "Furthermore, targeting the HLH motif in EIF3A could be used in conjunction with drugs that target parallel pathways, for example doxorubicin, a drug thought to inhibit transcription by targeting DNA topoisomerases, that is commonly used in the treatment of Burkitt’s lymphoma." (PMID 37768948, 2023).
coloboma (1 paper, 2025). An abnormality in which a part of a structure in one or both eyes is missing. "Notably, mutants also exhibited coloboma, a feature reported in one EIF3A individual (proband #16)." (PMID 41033306, 2025).
colorectal tumor (1 paper, 2022). "Collectively, these results further demonstrated the oncogenic role of eIF3a in colorectal tumor growth in vivo." (PMID 35300416, 2022). "Similar to eIF3a, RhoA and Cdc42 represent higher expression in colorectal tumor tissues compared to adjacent normal tissues." (PMID 35300416, 2022). "We first evaluated its expression in a panel of clinical samples and discovered notably differential eIF3a expression in colorectal tumors compared with normal tissues at both the mRNA and protein levels." (PMID 35300416, 2022). "Interestingly, patients with higher eIF3a expression presented poorer survival outcomes, whereas patients with lower eIF3a expression exhibited a better prognosis We then evaluated eIF3a expression in colorectal tumor tissues versus normal tissues." (PMID 35300416, 2022).
diabetes (1 paper, 2023). "High-throughput sequencing revealed that eIF3a is associated with estrogen receptor response, diabetes, and immune response." (PMID 37152897, 2023).
keloid (1 paper, 2025). An irregularly shaped, elevated mark on the skin caused by deposits of excessive amounts of collagen during wound healing. "Through this molecular mechanism, eIF3a silencing ameliorates the pathological processes of keloid formation by attenuating two key pathogenic features: excessive KF cell proliferation and aberrant overproduction of ECM components." (PMID 40346622, 2025).
left ventricular noncompaction (1 paper, 2025). Left ventricular noncompaction (LVNC) is a rare cardiomyopathy characterized anatomically by prominent left ventricular trabeculae and deep intratrabecular recesses causing progressive systolic and diastolic dysfunction, conduction abnormalities, and occasionally thromboembolic events. "Regarding EIF3A, a missense variant, c.1145A>G (GenBank: NM_003750.4) (p.Tyr382Cys), was found to segregate with left-ventricular noncompaction (LVNC) in two related individuals." (PMID 41033306, 2025).
lung diseases (1 paper, 2022). "For the majority of genes such as Elac2, Csnk1a1, Eif3a, Eif4g2, Tmed2 and Mpv17l, a role in the pathogenesis of lung diseases was indicated by previous studies, although their functions in the neonatal lung remain unexplored." (PMID 36271035, 2022).
lymph node metastasis (1 paper, 2013). "Analysed by GO database and KEGG pathways database, eIF3a and RPN2 which were low-expression in regional lymph node metastasis tissues were the most frequently selected genes affecting regional lymph node metastasis in our study and validated by qRT-PCR." (PMID 24386425, 2013).
lymphoma (1 paper, 2023). A malignant (clonal) proliferation of B- lymphocytes or T- lymphocytes which involves the lymph nodes, bone marrow and/or extranodal sites. "The fact that HLH* EIF3A is sufficient to lower MYC levels in these lymphoma cells and increase their sensitivity to chemotherapeutic compounds suggests that eIF3 could serve as a potential target for cancer therapeutic strategies." (PMID 37768948, 2023).
metastatic diseases (1 paper, 2022). "A higher eIF3a expression also indicated the tendency of metastatic diseases and poor prognosis, as typically noted for tumor promoters." (PMID 35300416, 2022). "Additionally, primary tumors exhibiting higher eIF3a expression are more likely to develop metastatic disease." (PMID 35300416, 2022). "Besides, patients with tumor metastasis exhibited significantly higher eIF3a expression than those with non-metastatic disease, demonstrating that approximately 60% of metastatic patients expressed moderate or strong eIF3a." (PMID 35300416, 2022).
nasopharyngeal carcinoma (1 paper, 2012). A carcinoma arising from the nasopharyngeal epithelium. "These were analysed for their eIF3a dependence in an in vitro model systems for nasopharyngeal carcinoma." (PMID 22619676, 2012).
pancreatic ductal adenocarcinoma (1 paper, 2022). An infiltrating adenocarcinoma that arises from the epithelial cells of the pancreas. "The role of eIF3a in cell migration has been studied in pancreatic ductal adenocarcinoma and hepatocarcinoma in vitro by conducting Transwell and wound healing assays." (PMID 35300416, 2022).
pulmonary hypertension (1 paper, 2025). Increased pressure within the pulmonary circulation due to lung or heart disorder. "Building on these findings, our current investigation focused on elucidating the functional relationship between eIF3a and pulmonary arterial hypertension progression, with a particular emphasis on uncovering its underlying molecular mechanisms." (PMID 40346622, 2025). "Notably, high expression of TGFβ1 and phosphorylation of SMAD2/3 in the rat pulmonary hypertension model were reversed by eIF3a knockdown, and the expression of these proteins was also significantly greater in the AAV1-shRNA-NC group than in the control group." (PMID 40346622, 2025). "Notably, eIF3a knockdown significantly attenuated the pulmonary hypertension-induced upregulation of these myofibroblast markers." (PMID 40346622, 2025). "Knockdown of eIF3a significantly inhibited the pulmonary arterial hypertension and vascular remodeling in MCT-induced PAH rat model, ameliorated MCT-induced increases of right ventricular systolic pressure (RVSP) and right ventricular hypertrophy (RVH) in rats." (PMID 40346622, 2025). "Subsequent analysis revealed significant upregulation of eIF3a expression in pulmonary hypertension tissues compared to normal controls." (PMID 40346622, 2025).
renal carcinoma (1 paper, 2021). A carcinoma arising from the epithelium of the renal parenchyma or the renal pelvis. "Univariate and multivariate Cox regression analyses demonstrated that EIF3A expression was associated with a poor prognosis in patients with renal cancer." (PMID 34923969, 2021). "Above all, the relationship of EIF3A and the infiltration of immune cells of different phenotypes can affect the occurrence and development of renal carcinoma." (PMID 34923969, 2021).
Right ventricular hypertrophy (1 paper, 2025). In this case the right ventricle is more muscular than normal, causing a characteristic boot-shaped (coeur-en-sabot) appearance as seen on anterior- posterior chest x-rays. "In summary, MCT induced pathological remodeling of the pulmonary artery and right ventricular hypertrophy in the PAH rat model, and these alterations may be related to the high expression of eIF3a in pulmonary arterial endothelial cells." (PMID 40346622, 2025).
squamous cell carcinoma (1 paper, 2012). A carcinoma arising from squamous epithelial cells. "By means of a tissue microarray (TMA) for histopathological and statistical assessment, we here show eIF3a expression in 103 cases of squamous cell carcinoma of the oral cavity (OSCC), representing tissues from 103 independent patients." (PMID 22619676, 2012).
squamous cell carcinoma of the cervix (1 paper, 2012). "On the other hand, studies in squamous cell carcinoma of the cervix and esophagus showed eIF3a expression to correlate with better prognosis." (PMID 22619676, 2012).
cancer (105 papers, 2002 to 2025). A tumor composed of atypical neoplastic, often pleomorphic cells that invade other tissues. "Pan-cancer analysis demonstrated that high eIF3a expression was associated with worse prognosis in several tumors." (PMID 38589831, 2024). "In previous studies, EIF3a was thought to be associated with the occurrence, metastasis, prognosis and treatment of cancer." (PMID 31197975, 2019). "With respect to EIF3A, it encodes the largest subunit of eIF3 complex involved in translational regulation, cell growth and cancer." (PMID 31156702, 2019). "This association of eIF3a with early development is paralleled with findings of an upregulation in cancer." (PMID 22619676, 2012). "Oppositely, KIAA1429, YTHDC2, and EIF3A associated pairs were only found in one cancer." (PMID 33718187, 2021). "We thus further hypothesize that high eIF3a expression level in variant cancer patients may contribute to better survival after receiving platinum chemotherapy." (PMID 26213845, 2015). "For example, elevated expression of eIF3a might be associated with oncogenesis in some cancers, and it is possibly implicated in regulating the expression of ribonucleotide reductase and p27 protein." (PMID 20462454, 2010). "However, further studies are required to interrogate the effect of HLH* EIF3A on MYC-addicted versus merely MYC-expressing cancer cells, as well as determine whether loss of MYC is the sole cause of the proliferation defect." (PMID 37768948, 2023). "The selective enhancement of translation initiation on cancer-associated transcripts by the EIF3A HLH motif highlights a new mode of eIF3 translation regulation and identifies a well-defined, discrete structural motif that could be targeted for future drug development efforts." (PMID 37768948, 2023). "The individual subunits of the eIF3 complex (eIF3a, eIF3b, eIF3c, eIF3e, eIF3h, and eIF3i) assume an additional role in regulating the translational initiation of specific mRNAs encoding proteins that promote cell growth and hence interfere in the development of cancer and tumor cells in humans." (PMID 34733303, 2021). "EIF3a is suggested to be correlated with cancer occurrence, metastasis, prognosis, and therapeutic response." (PMID 40055250, 2025). "It has also been shown that eIF3a knockdown reverses malignant phenotype of cancer cells, yet paradoxically increases their resistance to DNA-damaging chemotherapeutics by upregulating synthesis of DNA damage repair proteins." (PMID 39413959, 2024). "For example, small molecule mimosine, NCE22, and NCE30 showed cytotoxicity on tumor cells in vitro as the inhibitor of eIF3a, making these compounds candidates for eIF3a regulation with the potential to become anti-cancer agents." (PMID 39409166, 2024). "EIF3a expression is significantly increased by ~6 folds in cancer compared with the matched normal tissues." (PMID 39413959, 2024). "Our work also found that it was involved in lipid peroxidation; the knockdown of eIF3a elevated the ROS level when cancer cells were exposed to cytotoxic antitumor drugs (unpublished)." (PMID 37152897, 2023). "Meanwhile, eIF3a also regulated special mRNA translation involved in cancer incidence and development and affects the therapy of malignant tumors." (PMID 37152897, 2023). "Taken together, eIF3a accelerates the acquisition of the migratory phenotype of cancer cells by activating Cdc42 and RhoA expression at the translational level." (PMID 35300416, 2022). "Eukaryotic translation initiation factor 3 subunit A (eIF3a), the largest subunit of the eIF3 complex, has been shown to be overexpressed in malignant cancer cells, potentially making it a proto-oncogene." (PMID 35595099, 2022).